DEFB126 (defensin beta 126)
Description:
Highly glycosylated atypical beta-defensin involved in several aspects of sperm function. Facilitates sperm transport in the female reproductive tract and contributes to sperm protection against immunodetection; both functions are probably implicating the negative surface charge provided by its O-linked oligosaccharides in the sperm glycocalyx. Involved in binding of sperm to oviductal epithelial cells to form a sperm reservoir until ovulation. Release from the sperm surface during capacitation and ovaluation by an elevation of oviductal fluid pH is unmasking other surface components and allows sperm to penetrate the cumulus matrix and bind to the zona pellucida of the oocyte (By similarity). In vitro has antimicrobial activity and may inhibit LPS-mediated inflammation.
Synonyms: DEFB-26; C20orf8; DEFB26; bA530N10.1; HBD26; hBD-26
Tractability: Antibody: UniProt places it where antibodies can reach, with high confidence; UniProt predicts a signal peptide or a membrane-spanning region; its Gene Ontology location is reachable by antibodies, with medium confidence.
Gene: Protein-coding gene on chromosome 20 (142,590 to 145,751, forward strand). Ensembl gene ENSG00000125788.
Subcellular location: Secreted
Pathways (Reactome):
Immune System: Beta defensins; Defensins
Gene Ontology:
Biological process: antimicrobial humoral immune response mediated by antimicrobial peptide; defense response to Gram-negative bacterium
Cellular component: extracellular region
Genetic constraint (gnomAD): Loss-of-function variants: 1 observed, 2.21 expected, observed/expected ratio (o/e) 0.45, 90% interval 0.15 to 1.7. That is too few expected variants to judge how well the gene tolerates losing a copy. Missense variants: 133 observed, 141.46 expected, observed/expected ratio (o/e) 0.94, 90% interval 0.82 to 1.09. Synonymous variants: 50 observed, 47.24 expected, observed/expected ratio (o/e) 1.06, 90% interval 0.84 to 1.34.
Homologues: Orthologues: chimpanzee DEFB126 (90% identical).
Diseases named in the same sentence as DEFB126 in open-access papers:
DEFB126 is named in the same sentence as 2 diseases in open-access papers, as found by Europe PMC text mining. Sharing a sentence is not in itself a finding about the gene and the disease. The quoted sentences say what the papers report.
Infertility (1 paper, 2015). "In summary, our findings provided new hints of DEFB126 in the pathogenesis and possibly treatment of human infertility 22,29–31." (PMID 25721098, 2015).
cancer (1 paper, 2024). A tumor composed of atypical neoplastic, often pleomorphic cells that invade other tissues. "Nevertheless, we also recurrently identified some other candidate TAAs across many cancer types, such as GNGT1 in 23 cancer types, USP41 in 17 cancer types, and DEFB126 in 16 cancer types." (PMID 39561714, 2024).